RIPK3 (receptor interacting serine/threonine kinase 3)
Diseases named in the same sentence as RIPK3 in open-access papers (continued):
Sharing a sentence is not in itself a finding about the gene and the disease.
atherosclerosis (continued). "It has already been well established that the microbiome can influence atherosclerosis, thus microbiota that differentially affect inflammatory pathways could also differentially affect RIPK3 activation." (PMID 31953345, 2020). "If previous reports are correct that RIPK3 increases atherosclerosis severity and that necroptotic macrophages are the main source of that increase in severity, then we would expect to see less atherosclerotic phenotypic severity in the Ripk3ΔGlobal, Ripk3ΔHet, and Ripk3ΔMΦ-Cre mice." (PMID 31953345, 2020). "In addition, the upward trends in E-selectin and in CD11b expression in Ripk3ΔEC-Cre aortas provide further indications that RIPK3 activity suppresses inflammation in a cell-type specific manner during atherosclerosis." (PMID 31953345, 2020). "One important question that arises from our findings is whether RIPK3-mediated necroptosis suppresses inflammation during atherosclerosis progression, as has been suggested for the cultured mouse fibroblast study cited above." (PMID 31953345, 2020). "Interestingly, RIPK3 gene expression in macrophages increases during the development of atherosclerosis, which suggests that macrophage necroptosis plays a role in advanced plaques." (PMID 31019462, 2019). "However, there has been no study revealing that Cd could impair macrophage mitochondrial homeostasis and promote macrophage polarization contributing to atherosclerosis via regulating RIPK3 signaling." (PMID 34820428, 2021). "Thus, we suspect that the main role of RIPK3 in atherosclerosis is not to cause macrophage necroptosis, but rather to prevent macrophages and endothelial cells from becoming pro-inflammatory." (PMID 31953345, 2020). "Furthermore, RIPK3 is expressed in a multitude of cell types, suggesting that it may be physiologically relevant to more than just macrophages in atherosclerosis." (PMID 31953345, 2020). "Finally, mice deficient in phospholipid transfer protein (PLTP), a protein known to correlate with atherosclerosis severity, showed reduced levels of RIPK3 in atherosclerotic plaques in addition to reduced atherosclerotic lesion burden and intra-lesion cell death." (PMID 33142926, 2020). "Meanwhile, the RIPK1/RIPK3/MLKL pathway-mediated necroptosis plays a significant role in various CVDs, including atherosclerosis, ischemia-reperfusion injury, myocardial infarction, and myocarditis." (PMID 39301029, 2024). "RIPK3 and MLKL have been demonstrated to mediate macrophage necroptosis during atherosclerosis development." (PMID 37863894, 2023). "Cumulatively, the data suggest that RIPK1 is emerging as a master switch that controls inflammation and cell survival in atherosclerosis progression, and phosphorylation of RIPK1, RIPK3 and MLKL are definitive indicators of necroptosis activation." (PMID 37863894, 2023). "At baseline (0 weeks WD), very low levels of RIPK1, RIPK3, and MLKL were observed in the atherosclerosis-prone aortic arch of both ApoE−/− and ApoE−/− Fbn1C1039G+/− mice but the expression levels increased during plaque progression." (PMID 35625752, 2022). "According to previous studies, expression of RIPK3 and MLKL mRNA increases in atherosclerotic plaques, whereas RIPK3 KO mice with atherosclerosis exhibit reduced inflammation followed by death." (PMID 36110858, 2022). "In atherosclerosis, elevated levels of RIPK1, RIPK3, and phosphorylated MLKL have been detected in unstable atherosclerotic plaques from humans and Ripk3-deficient mice develop significantly smaller advanced aortic atherosclerotic lesions." (PMID 34572045, 2021). "Levels of RIPK3 as well as RIPK1 are elevated in human tissues affected by various pathological conditions, including ischemic stroke, atherosclerosis, and aortic aneurysm." (PMID 34867386, 2021).
atherosclerosis (continued). "More recently, another study reported that loss of RIPK3 in smooth muscle cells (or globally) does not affect lesion size and necrotic core, whereas RIPK3 deletion in macrophages or endothelial cells exacerbates atherosclerosis." (PMID 35625752, 2022). "The expression of RIPK3 and MLKL are both increased in human and mouse atherosclerosis." (PMID 39872161, 2022). "Consistent with studies on RIPK3, recently a study indicates MLKL may directly contribute to atherosclerosis lesion development and necrotic core formation." (PMID 34867386, 2021). "Altogether, these data suggest that RIPK3 in macrophages and endothelial cells protects against atherosclerosis through a mechanism that likely does not involve necroptosis." (PMID 31953345, 2020). "To try to understand how Ripk3 deletion in endothelial cells could lead to an increase in atherosclerosis severity, we utilized a cultured murine pancreatic endothelial cell line (MS1 cell line), which we chose for this study because it expresses high levels of endogenous RIPK3." (PMID 31953345, 2020). "Unlike RIPK3 and MLKL, RIPK1 has been identified as a central driver of inflammation in atherosclerosis by promoting the release of inflammatory cytokines through the NF‐κB pathway, which is independent of necroptosis‐associated pathways." (PMID 38873710, 2024).
hepatocellular carcinoma (25 papers, 2019 to 2025). A malignant tumor that arises from hepatocytes. "In hepatocellular carcinoma, the functional deficiency of receptor-interacting protein kinase 3 (RIPK3) inhibits caspase-1 dependent PPAR cleavage, and the accumulation of PPAR augments the FAO and M2-like polarization of TAMs." (PMID 37740232, 2023). "For example, deficiency of RIPK3 in hepatocellular carcinoma promotes TAMs infiltration levels and M2-like TAM polarization through the lipid metabolism pathway in TME." (PMID 36142328, 2022). "Commonly used human hepatoma cell lines showed a methylation-dependent loss of RIPK3 expression with a block in the activation of the necroptotic pathway, suggesting that evasion from necroptosis is an important step in hepatocyte malignant transformation." (PMID 32326539, 2020). "Deficiency of RIPK3 in hepatocellular carcinoma is reported to increase M2 tumor-associated macrophages population associated with antitumor immunity, also leading to the conclusion that RIPK3 suppresses the protumorigenic effects of the immune system in favor of the antitumor immunogenic responses." (PMID 40010643, 2025). "Macrophages (TAMs) play important roles in tumor growth, invasion, angiogenesis and metastasis, and receptor-interacting protein kinase 3 (RIPK3) is down-regulated in hepatocellular carcinoma (HCC)-associated macrophages." (PMID 35743814, 2022). "On the other hand, receptor-interacting protein kinase 3 (RIPK3), a central factor in necroptosis, is downregulated in hepatocellular carcinoma- (HCC-) associated TAMs." (PMID 34476174, 2021). "RIPK3 has been found to modulate the lipid metabolic reprogramming of tumor-associated macrophages, thereby regulating the immunometabolism 27 and facilitating immune evasion 28 in hepatocellular carcinoma (HCC)." (PMID 38164277, 2024). "We examined the effects of ATF3 on Ripk3 expression using H4IIE rat hepatoma cells." (PMID 36690638, 2023). "RIPK3 knockdown resulted in increased MDSC recruitment in a mouse model of hepatocellular carcinoma, which could be inhibited by a CXCR2 antagonist." (PMID 36110844, 2022). "In hepatocellular carcinoma (HCC), downregulation of RIPK3 induces fatty acid oxidation within the TME, facilitating M2 polarization of TAMs and subsequently driving tumor initiation and progression." (PMID 39575419, 2024). "In hepatocellular carcinoma (HCC) patients, increased RIPK1, RIPK3, and phosphorylated MLKL levels were positively correlated with increases in tumor-infiltrating CD3+ and CD8+ T-lymphocytes." (PMID 38799433, 2024). "MLKL can also trigger necroptosis independently of Ripk3 in tanshinol A-induced lung cancer cell death, anti-CD147 antibody-induced hepatocellular carcinoma cell death, radiation-induced antitumor immunity, and autoimmune hepatitis." (PMID 36828808, 2023). "Recently, it is increasingly noted that RIPK3 is intrinsically silenced in hepatocytes, raising a question about the role of MLKL in hepatocellular carcinoma (HCC)." (PMID 36650126, 2023). "A recent study showed that RIPK3 was a critical regulator in the malignant transformation of hepatocellular carcinoma (HCC) and that to regulate necroptosis may improve the chemosensitivity of HCC10." (PMID 36175606, 2022). "They confirmed the expression of RIPK1, RIPK3, and MLKL, which are important molecules for necroptosis, in HepG2 hepatocellular carcinoma cells, primary human hepatocytes (pHep), and primary human macrophages (pMФ)." (PMID 35806184, 2022). "Decreased receptor-interacting protein kinase 3 (RIPK3) expression was found to be correlated with increased MDSC number and activity in colorectal and hepatocellular carcinoma, likely mediated by the NF-κB/COX-2/PGE2 axis." (PMID 36110844, 2022). "Necroptosis related proteins RIPK1, RIPK3 and MLKL were highly expressed in hepatocellular carcinoma cells and tumor tissues with Sorafenib treatment, which means that Sorafenib activated the necroptosis pathway in vitro and in vivo." (PMID 33440739, 2021).
hepatocellular carcinoma (continued). "Furthermore, RIPK3 re-activation by the demethylation of its promoter can re-sensitize tumor cell lines to chemotherapy, opening a new approach for hepatocellular carcinoma (HCC) treatment." (PMID 32326539, 2020). "For instance, high RIPK3 expression predicted a favorable prognosis in colorectal cancer (CRC), whereas low RIPK1 expression contributed to an unfavorable prognosis in hepatocellular carcinoma (HCC)." (PMID 35711565, 2022).
acute kidney injury (24 papers, 2015 to 2025). Sudden and sustained deterioration of the kidney function characterized by decreased glomerular filtration rate, increased serum creatinine or oliguria. "Consistent with this, deficiency of RIPK3 or MLKL prevents oxalate crystal-induced acute kidney injury." (PMID 26817517, 2016). "This study aimed to assess the utility of TRAIL and RIPK3 in predicting mortality and acute kidney injury (AKI) among unselected intensive care unit (ICU) patients." (PMID 41009652, 2025). "Deletion of RIPK3 or MLKL can hinder oxalate crystal-induced acute kidney injury and renal damage in a mouse model of renal ischemia-reperfusion injury, among other effects." (PMID 37954576, 2023). "AZD5432 was discovered as a novel RIPK3 inhibitor for acute kidney injury (AKI) treatment by using virtual screening method." (PMID 38129399, 2023). "Conversely, inhibition of RIPK3 was shown to reduce the apoptosis in tubular epithelial cells and improve renal function in mice with LPS‐induced acute kidney injury." (PMID 35106914, 2022). "In septic acute kidney injury, upregulated RIPK3 contributes to lysosomal dysfunction and the accumulation of autophagosomes in renal proximal tubular epithelial cells." (PMID 35402535, 2022). "A strong evidence reported that RIPK3-dependent mitochondrial dysfunction led to compromised kidney tubular epithelial cell function, contributing to acute kidney injury." (PMID 32182211, 2020). "We subsequently showed that plasma RIPK3 measured 48 h after presentation was associated with RBC transfusions and acute kidney injury (AKI) in 80 trauma patients." (PMID 31253195, 2019). "RIPK1 KD mutants, RIPK3, and MLKL deficiency could alleviate acute kidney injury by decreasing necroptosis." (PMID 34977874, 2021). "Furthermore, we showed that Ripk3−/− to Ripk3+/+ or Mlkl−/− to Mlkl+/+ chimeric mice developed similar renal failure and serious tubular injury at an early stage of IRI compared with chimeric mice from WT donors." (PMID 30158627, 2018). "Overall, our data reveal the relevance of RIPK3-pMLKL regulation for acute kidney injury and identifies an FDA-approved drug that may be useful for immediate clinical evaluation of inhibition of pro-death RIPK1/RIPK3 activities in human diseases." (PMID 29500402, 2018). "We found that both wild type and RIPK3-deficient mice, whether male or female, developed similarly high levels of blood urea nitrogen (BUN), indicating renal failure." (PMID 27669412, 2016). "Receptor-interacting protein kinase 3 (RIPK3) damages lysosomes in sepsis-induced acute kidney injury (S-AKI)." (PMID 40129990, 2025). "In acute kidney injury (AKI) models, miR-223-3p was obviously increased during 3-MCPD-dipalmitate-induced AKI, which inhibited RIPK3 expression by targeting the 3′ un-translated region of RIPK3." (PMID 34381023, 2021). "The authors conclude that 3-MCPD can induce renal toxicity, inducing tubular cell death by activating the RIPK1/RIPK3/MLKL-related necroptosis pathway, generating acute kidney injury, and activating the programmed cell death pathway of tubular cells in kidney tissue." (PMID 40137488, 2025). "Among the investigated pathologies, necroptosis also demonstrates its implication in kidney diseases; indeed, both acute kidney injury (AKI) and chronic kidney disease (CKD) report increased levels of RIPK1, RIPK3, and MLKL, suggesting necroptosis as a crucial event in kidney injuries." (PMID 35682876, 2022). "Lack of RIPK3 can protect against renal tubular injury in acute kidney injury induced by sepsis." (PMID 37954576, 2023). "Lacking RIPK3 protects kidney tubular injury in the sepsis-induced acute kidney injury." (PMID 32613000, 2020). "Ripk3+/+ to Ripk3+/+ chimeric mice developed renal failure and serious tubular injury as determined by PAS staining at 2 and 14 days after IRI, but those characteristic symptoms were significantly reduced in Ripk3+/+ to Ripk3−/− and Ripk3−/− to Ripk3−/− chimeras." (PMID 30158627, 2018).
influenza (21 papers, 2016 to 2025). An acute viral infection of the respiratory tract, occurring in isolated cases, in epidemics, or in pandemics; it is caused by serologically different strains of viruses (influenzaviruses) designated A, B, and C, has a 3-day incubation period, and usually lasts for 3 to 10 days. "recently reported that inhibition of necroptosis by UH15-38, a RIPK3-specific inhibitor, or by MLKL deficiency, blocks H1N1 virus (PR8)-induced lung injury in a mouse model of severe influenza." (PMID 39811662, 2025). "Simultaneous activation of multiple cell death pathways involving RIPK3 and caspase-8/caspase-1 is proposed to occur during infection by a number of pathogens including Legionella, Francisella, influenza, and Yersinia." (PMID 39058785, 2024). "Necroptosis, mediated by RIPK1 and RIPK3, is a significant contributor to tissue damage during influenza infections." (PMID 39591329, 2024). "RIPK3 regulates type I IFN production during influenza infection (, however, we observed normal production of type I IFNs in response to IOE infection in Ripk3Δintron2 mice." (PMID 30080899, 2018). "For example, cIAP2-dependent antagonism of RIPK3-mediated programmed necrosis critically protects the host from influenza infection." (PMID 26795495, 2016). "Inhibitors of RIPK3 kinase activity prevent lung injury in mouse models of severe influenza." (PMID 39345610, 2024). "The earlier observations indicating predominant apoptosis activation in influenza-infected cells could be because of the usage of transformed human cell lines, like A549 and HeLa, which lack RIPK3 expression." (PMID 35587190, 2022). "RIPK3/necroptosis studies appear to generate contradictory results as to whether necroptosis protects against or is detrimental during influenza infection." (PMID 31461941, 2019). "Moreover, RIPK3 knockout protects cIAP2-deficient mice from lethal IAV H1N1 infection via maintenance of pulmonary tissue homeostasis and mice from influenza H7N9 infection via inhibition of host inflammatory response, respectively." (PMID 31440477, 2019). "Following influenza challenge, RIPK3 has been shown to activate caspase-816." (PMID 29643440, 2018). "Additionally, caspase-6 has been shown to enhance necroptosis during influenza infection by promoting the RHIM-dependent interaction between ZBP1 and RIPK3, thereby facilitating both necroptosis and apoptosis." (PMID 39591329, 2024). "Interestingly, active immunization of Ripk3−/− mice with recombinant M2e-VLPs could raise equal titers of M2e-specific serum IgG antibodies as compared to immunization of Ripk3+/+ mice, but this apparently does not result in a protective effect against a lethal influenza challenge." (PMID 35351865, 2022).
acute myeloid leukemia (20 papers, 2015 to 2025). Acute myeloid leukemia (AML) is a group of neoplasms arising from precursor cells committed to the myeloid cell-line differentiation. "However, the downregulation of another key member, RIPK3, is associated with low survival in acute myeloid leukemia, suggesting its antitumor effects through facilitating RIPK3-MLKL-mediated necroptosis and the differentiation of leukemia-initiating cells." (PMID 40229837, 2025). "For example, RIPK3 was significantly decreased in breast cancer, colorectal cancer, acute myeloid leukemia (AML), and melanoma." (PMID 35814424, 2022). "For example, RIPK3 expression is significantly down-regulated in patients with acute myeloid leukemia (AML)." (PMID 36238158, 2022). "Several studies have shown that loss of expression of the receptor-interacting serine/threonine protein kinase 3 (RIPK3), an essential mediator of necroptotic cell death, promotes the development of cancer, including acute myeloid leukaemia." (PMID 32555451, 2020). "For instance, epigenetic events (mostly DNA methylation-driven) can cause RIPK3 protein suppression in several human cancer cell lines, including breast cancer, colorectal cancer (CRC) and acute myeloid leukemia (AML) (in nearly 2/3rd of >60 human cell lines tested)." (PMID 32752206, 2020). "AXL expression levels also negatively correlated with RIPK3 expression in stomach adenocarcinoma tumors and acute myeloid leukemia, based on the analysis of the Cancer Genome Atlas (TCGA) database using cBio Cancer Genomics Portal and according to both Pearson and Spearman correlation analyses." (PMID 30157175, 2018). "Molm-13, an acute myeloid leukaemia (AML) cell line, expresses RIPK3 and is known to undergo necroptosis." (PMID 32457484, 2020). "In acute myeloid leukemia (AML), RIPK3 signaling might be epigenetically repressed in leukemic cells isolated from a subgroup of AML patients such as AML with RUNX1-ETO or FLT3-ITD mutations." (PMID 35561683, 2022). "However, the expression of RIPK3 and MLKL is reduced in various cancer cells, including breast cancer, colorectal cancer, acute myeloid leukemia, and nonsmall cell lung cancer." (PMID 39872161, 2022). "Hence, RIPK3 expression is downregulated in many cancer cell lines as well as in several human cancers, including breast cancer, colorectal cancer (CRC), acute myeloid leukemia (AML) and melanoma." (PMID 33050394, 2020).